MIPEP (mitochondrial intermediate peptidase)
Description:
Cleaves proteins, imported into the mitochondrion, to their mature size.
Synonyms: MIP; COXPD31; HMIP
Tractability: PROTAC: ubiquitination databases record sites on it; its protein half-life has been measured.
Gene: Protein-coding gene on chromosome 13 (23,730,176 to 23,889,448, reverse strand). Ensembl gene ENSG00000027001.
Subcellular location: Mitochondrion matrix
Subcellular location (Human Protein Atlas): Mitochondria
Gene Ontology:
Molecular function: protein binding; metalloendopeptidase activity; metallopeptidase activity
Biological process: protein processing; proteolysis
Cellular component: mitochondrion; mitochondrial matrix
Genetic constraint (gnomAD): Loss-of-function variants: 53 observed, 56.4 expected, observed/expected ratio (o/e) 0.94, 90% interval 0.75 to 1.18. The upper end of that interval is the gene's LOEUF score, 1.18, which puts it in group 5 of 6, group 1 being the genes least tolerant of losing a copy. Missense variants: 746 observed, 677.9 expected, observed/expected ratio (o/e) 1.1, 90% interval 1.03 to 1.17. Synonymous variants: 283 observed, 239.7 expected, observed/expected ratio (o/e) 1.18, 90% interval 1.07 to 1.3.
Gene-disease validity (ClinGen):
ClinGen rates the evidence that MIPEP causes each of these diseases.
mitochondrial disease (autosomal recessive): Moderate.
Homologues: Orthologues: macaque MIPEP (98% identical), dog MIPEP (92% identical), rabbit MIPEP (89% identical), guinea pig MIPEP (87% identical), rat Mipep (85% identical), mouse Mipep (84% identical), chimpanzee MIPEP (80% identical), pig MIPEP (79% identical), tropical clawed frog mipep (73% identical), zebrafish mipepa (70% identical), zebrafish mipepb (67% identical), Drosophila melanogaster CG7791 (48% identical), and 1 more. Paralogues in human: NLN (24% identical), THOP1 (24% identical).
Diseases named in the same sentence as MIPEP in open-access papers:
MIPEP is named in the same sentence as 22 diseases in open-access papers, as found by Europe PMC text mining. Sharing a sentence is not in itself a finding about the gene and the disease. The quoted sentences say what the papers report.
cardiomyopathy (4 papers, 2016 to 2024). A disease of the heart muscle or myocardium proper. "The mutations in MIPEP affect mitochondrial protein homeostasis, causing cardiomyopathy and aging, even contributing to lung cancer susceptibility." (PMID 39004717, 2024). "Several of the disorders associated with cardiomyopathy involve genes important for preprotein processing, such as MIPEP, XPNPEP3, CLPB, and HTRA2." (PMID 35328774, 2022). "Genes important in these processes and that are associated with cardiomyopathy include DNAJC19, MAGMAS, TIMM50, MIPEP, XPNPEP3, HTRA2, CLPB and HSPD1." (PMID 35328774, 2022). "Given that patient 1 with LVNC and cardiomyopathy was initially suspected to have a mitochondrial disorder, MIPEP was prioritized to be an excellent candidate gene given its fundamental role in mitochondrial biogenesis." (PMID 27799064, 2016). "Mutations in the MIPEP gene caused COXPD31/Eldomery–Sutton syndrome, a recessive disorder with developmental delay, cardiomyopathy, cataracts, hypotonia, left ventricular non-compaction, variable seizures." (PMID 34651031, 2021). "Mutations in the MIPEP gene, which encodes MIP, causes COXPD31/Eldomery–Sutton syndrome with developmental delay, cardiomyopathy, left ventricular non-compaction, hypotonia, and infantile death." (PMID 34651031, 2021).
developmental delay (3 papers, 2021 to 2025). "Pathogenic mutations within the MIPEP gene contribute to combined oxidative phosphorylation deficiency 31 (COXPD31, MIM #617228), characterised by left ventricular non-compaction, developmental delay, seizures and hypertonia." (PMID 40857737, 2025). "Additionally, ARFGEF2, MIPEP, NONO, SH2B1, and TMEM70 led to LVNC complicating developmental delay." (PMID 34819141, 2021).
breast carcinoma (2 papers, 2022 to 2024). "STRING analysis found ESF1 and MIPEP were the hub genes in breast cancer, whose increased expressions were verified by the IHC staining and western blot." (PMID 39004717, 2024). "Subsequent immunohistochemical staining validated the significant upregulation of ESF1 and MIPEP in the ER + breast cancer tissue sections." (PMID 39004717, 2024). "MIPEP appeared to specifically influence the process of proliferation, which may serve as a potential therapeutic target for breast cancer treatment." (PMID 39004717, 2024). "The upregulation of ESF1 and MIPEP promoted ER + breast cancer proliferation, which might provide novel targets for the development of new therapies." (PMID 39004717, 2024). "The upregulation of MIPEP expression may promote cell proliferation by enhancing the energy metabolism of breast cancer cells." (PMID 39004717, 2024). "Therefore, ESF1 and MIPEP proteins played a considerable role in ER + breast cancer development, which might serve as potential therapeutic targets." (PMID 39004717, 2024). "Our study revealed for the first time that MIPEP was upregulated in human breast cancer tissue and could promote the proliferation of MCF-7 cells by promoting colony formation and accelerating the cell cycle, without exerting an impact on cell migration ability." (PMID 39004717, 2024). "During STRING analysis, we found ESF1, MIPEP, TMEM24, and SART1 were the hub genes in ER + breast cancer’s pathogenesis." (PMID 39004717, 2024). "As the novel proteins discovered in ER + breast cancer, the functions of ESF1 and MIPEP were further discussed and verified in this study." (PMID 39004717, 2024).
lung carcinoma (2 papers, 2017 to 2024). "The SNP rs753955 was located in the intron at 13q12.12 region between MIPEP and TNFRSF19 identified as a risk locus of lung cancer by recent GWA studies." (PMID 28903315, 2017).
prostate carcinoma (2 papers, 2015 to 2021). A carcinoma that arises from epithelial cells of the prostate gland. "Furthermore, five other miPEPs in M. truncatula and A. thaliana and two other miPEPs (miPEP-200a and miPEP-200b) in prostate cancer cells have been identified." (PMID 34199614, 2021). "Transcriptome sequencing of these samples revealed a SLC45A3-SKIL fusion in LuCaP-77 and a MIPEP-SKIL fusion in the clinical sample, confirming SKIL as a recurrent 3′ fusion partner in prostate cancer." (PMID 25749039, 2015).
cataract (1 paper, 2016). Partial or complete opacity of the crystalline lens of one or both eyes that decreases visual acuity and eventually results in blindness. "Phenotypic evaluation following the identification of biallelic MIPEP variants in four patients identified a shared and rare syndrome of LVNC, DD, seizures, hypotonia, cataracts, and infantile/early childhood death." (PMID 27799064, 2016).
epilepsy (1 paper, 2025). A brain disorder characterized by episodes of abnormally increased neuronal discharge resulting in transient episodes of sensory or motor neurological dysfunction, or psychic dysfunction. "There were 8 proteins shared between epilepsy and ischemic stroke: SH3BGRL3, BPNT1, PTPMT1, PACSIN3, MIPEP, CMC2, ABCA5, and PTK2B." (PMID 40624693, 2025).
Insulin resistance (1 paper, 2024). Increased resistance towards insulin, that is, diminished effectiveness of insulin in reducing blood glucose levels. "Because of the well-established association between adiposity and insulin resistance we hypothesised that miPEP deficient mice might be protected against insulin resistance." (PMID 38960128, 2024). "To gain a deeper understanding of the potential role of this peptidase in insulin resistance, we developed and characterised the first adipocyte-specific miPEP knockout mouse model (adipo-miPEP-KO)." (PMID 38960128, 2024). "Strikingly, and in contrast to our predictions, adipo-miPEP-KO mice were protected against diet-induced insulin resistance and obesity." (PMID 38960128, 2024). "Here we demonstrate that the adipocyte mitochondrial proteome is markedly altered across multiple models of insulin resistance and reveal a consistent decrease in the level of the mitochondrial processing peptidase miPEP." (PMID 38960128, 2024). "Overall, these data suggest that miPEP deletion in adipocytes is sufficient to confer protection against diet-induced obesity and insulin resistance." (PMID 38960128, 2024). "Given that miPEP was significantly downregulated in insulin resistance, we next sort to evaluate the in vivo roles of miPEP in insulin resistance." (PMID 38960128, 2024). "•Adipocyte-specific miPEP deletion confers protection against diet-induced obesity and insulin resistance." (PMID 38960128, 2024). "To experimentally test this observation, we generated adipocyte-specific miPEP knockout mice to interrogate its role in the aetiology of insulin resistance." (PMID 38960128, 2024). "•The mitochondrial peptidase miPEP is consistently downregulated in insulin resistance." (PMID 38960128, 2024). "Only the mitochondrial processing peptidase miPEP and the ATP-dependent proteases PIRTM1 and AFG3L2 were downregulated across all insulin resistance models." (PMID 38960128, 2024).
left ventricular non-compaction cardiomyopathy (1 paper, 2021). "Mutations in the MIPEP gene, (encoding the octapeptidyl peptidase MIP, also known as Oct1 in yeast) have been found associated with left ventricular non-compaction cardiomyopathy (LVNC), hypotonia and developmental delay." (PMID 34356047, 2021).
myopia (1 paper, 2024). "Moreover, 4q25 rs10034228, 15q14 variation rs524952, and MIPEP variation rs9318086 were significantly concerned in myopia and different myopia severity in southern Chinese people, which together increased the susceptibility risk of high myopia by ten times." (PMID 38660258, 2024).
spastic ataxia (1 paper, 2025). "Additionally, individuals with deletion of the entire SGCG gene also lacked five other genes, among which SACS and MIPEP are reported to cause spastic ataxia and combined oxidative phosphorylation deficiency 31, respectively." (PMID 39755676, 2025).
cancer (2 papers, 2013 to 2018). A tumor composed of atypical neoplastic, often pleomorphic cells that invade other tissues. "ncRNA encoded peptides/proteins (HOXB-AS3, FBXW7-185aa, SHPRH-146aa, miPEP-200a, and miPEP-200b) have been proved to suppress tumorigenesis, which has enriched the research of ncRNAs in cancer development." (PMID 30483132, 2018). "Whether these cancer-suppressive peptides/small proteins (SPAR, HOXB-AS3, FBXW7-185aa, SHPRH-146aa, miPEP-200a, and miPEP-200b) encoded by ncRNAs, are secreted into human serum remains unknown." (PMID 30483132, 2018). "MIPEP expression was also significantly increased (p < 0.05) in grade II tumors comparing to the grade I. We also showed significantly (p < 0.05) and highly significant (p < 0.001) decreased expression of MAGI3 and ZFP37 (respectively) in the most malignant tumors." (PMID 23844591, 2013).
tumor (2 papers, 2022 to 2023). "According to the analysis of the TCGA data, the expression of MIPEP and NFS1 was higher in tumor tissues in comparison with that in normal tissues; however, the expression of CPT2 and ISCU was lower in tumor tissues in relative to that in normal tissues." (PMID 36776001, 2023).
metabolic disease (1 paper, 2024). A congenital disorder (due to inherited enzyme abnormality) or acquired (due to failure of a metabolically important organ) disorder resulting from an abnormal metabolic process. "Since we predicted that miPEP might play a role in metabolic disease we next examined the metabolic phenotype of KO mice." (PMID 38960128, 2024).
neurodegenerative disease (1 paper, 2015). A disorder of the central nervous system characterized by gradual and progressive loss of neural tissue and neurologic function. "In humans, MIPEP is highly expressed in heart and skeletal muscle and thought to play a role in neurodegenerative disease." (PMID 26710100, 2015).
MIPEP also shares sentences with these, for which no sentence is quoted: autism (1 paper); Glucose intolerance (1); hemoglobinopathy (1); ischemic stroke (1); Obesity (1); sickle cell anaemia (1); α-thalassemia (1).